MIR346 (microRNA 346)
Synonyms: hsa-mir-346; MIRN346; miR-346; miRNA346
Gene: MicroRNA gene on chromosome 10 (86,264,694 to 86,264,788, reverse strand). Ensembl gene ENSG00000199104.
Gene Ontology:
Biological process: miRNA-mediated post-transcriptional gene silencing
Cellular component: RISC complex
Homologues: Orthologues: chimpanzee ptr-mir-346 (100% identical), macaque MIR346 (100% identical), dog MIR346 (97% identical), rabbit MIR346 (97% identical), mouse Mir346 (93% identical), rat Mir346 (91% identical).
Diseases named in the same sentence as MIR346 in open-access papers:
MIR346 is named in the same sentence as 1 disease in open-access papers, as found by Europe PMC text mining. Sharing a sentence is not in itself a finding about the gene and the disease. The quoted sentences say what the papers report.
cervical cancer (1 paper, 2020). A primary or metastatic malignant neoplasm involving the cervix. "MIR346 binds to a region in the 3′UTR of TERT mRNA in human cervical cancer cells and astrocytic glioma cells, leading to upregulating TERT expression." (PMID 32680564, 2020).